RNU6-1325P (RNA, U6 small nuclear 1325, pseudogene)
Gene: Small nuclear RNA gene on chromosome 4 (59,834,063 to 59,834,167, forward strand). Ensembl gene ENSG00000201775.
Homologues: Orthologues: chimpanzee U6 (97% identical), macaque U6 (88% identical), dog U6 (79% identical), guinea pig U6 (68% identical), dog U6 (63% identical). Paralogues in human: RNU6-211P (85% identical), RNU6-1152P (84% identical), RNU6-1145P (83% identical), RNU6-20P (83% identical), RNU6-820P (83% identical), RNU6-921P (83% identical), RNU6-1122P (82% identical), RNU6-1214P (82% identical), RNU6-144P (82% identical), RNU6-15P (82% identical), RNU6-19P (82% identical), RNU6-310P (82% identical), and 1285 more.